HPS4 (HPS4 biogenesis of lysosomal organelles complex 3 subunit 2)
Description:
Component of the BLOC-3 complex, a complex that acts as a guanine exchange factor (GEF) for RAB32 and RAB38, promotes the exchange of GDP to GTP, converting them from an inactive GDP-bound form into an active GTP-bound form. The BLOC-3 complex plays an important role in the control of melanin production and melanosome biogenesis and promotes the membrane localization of RAB32 and RAB38.
Synonyms: KIAA1667; LE; BLOC3S2
Tractability: Antibody: the Human Protein Atlas places it where antibodies can reach. PROTAC: ubiquitination databases record sites on it.
Gene: Protein-coding gene on chromosome 22 (26,443,107 to 26,483,931, reverse strand). Ensembl gene ENSG00000100099.
Subcellular location (Human Protein Atlas): Plasma membrane
Pathways (Reactome):
Vesicle-mediated transport: RAB GEFs exchange GTP for GDP on RABs
Gene Ontology:
Molecular function: guanyl-nucleotide exchange factor activity; protein binding; protein dimerization activity; protein homodimerization activity; small GTPase binding
Biological process: lysosome organization; melanosome assembly; positive regulation of establishment of protein localization to mitochondrion; protein stabilization; protein targeting; hemostasis; platelet dense granule organization; positive regulation of eye pigmentation; vesicle-mediated transport
Cellular component: BLOC-3 complex; cytoplasm; lysosome; melanosome; membrane; platelet dense granule; cytoplasmic vesicle; cytosol; lysosomal membrane
Genetic constraint (gnomAD): Loss-of-function variants: 40 observed, 65.58 expected, observed/expected ratio (o/e) 0.61, 90% interval 0.47 to 0.79. The upper end of that interval is the gene's LOEUF score, 0.79, which puts it in group 3 of 6, group 1 being the genes least tolerant of losing a copy. Missense variants: 857 observed, 904.93 expected, observed/expected ratio (o/e) 0.95, 90% interval 0.89 to 1. Synonymous variants: 372 observed, 368.57 expected, observed/expected ratio (o/e) 1.01, 90% interval 0.93 to 1.1.
Gene-disease validity (ClinGen):
ClinGen rates the evidence that HPS4 causes each of these diseases.
Hermansky-Pudlak syndrome 4 (autosomal recessive): Definitive.
Homologues: Orthologues: chimpanzee HPS4 (98% identical), macaque HPS4 (93% identical), pig HPS4 (71% identical), dog HPS4 (71% identical), guinea pig HPS4 (70% identical), rabbit HPS4 (69% identical), mouse Hps4 (61% identical), rat Hps4 (56% identical), tropical clawed frog hps4 (44% identical), zebrafish hps4 (35% identical), Drosophila melanogaster HPS4 (19% identical).
Diseases named in the same sentence as HPS4 in open-access papers:
HPS4 is named in the same sentence as 33 diseases in open-access papers, as found by Europe PMC text mining. Sharing a sentence is not in itself a finding about the gene and the disease. The quoted sentences say what the papers report.
pulmonary fibrosis (6 papers, 2021 to 2025). Chronic progressive interstitial lung disorder characterized by the replacement of the lung tissue by connective tissue, leading to progressive dyspnea, respiratory failure, or right heart failure. "HPS4 participates in the biogenesis of melanosomes, platelet dense granules, and lysosomes, and mutations in HPS4 result in Hermansky-Pudlak syndrome characterized by albinism, excessive bleeding, and pulmonary fibrosis." (PMID 34445083, 2021). "Importantly, in patients harboring HPS1 and HPS4 mutations, pulmonary fibrosis is highly penetrant and a leading cause of premature death in adulthood, typically around the fourth or fifth decades of life, secondary to respiratory failure." (PMID 33808351, 2021). "HPS progressive pulmonary fibrosis is primarily associated with dysfunction of the subunits HPS1 and HPS4 in BLOC-3 and the subunit HPS2 in the AP-3 complex." (PMID 39457053, 2024). "Studies have shown that HPS1 or HPS4 lung fibers are more prone to developing pulmonary fibrosis during middle age, between the ages of 30 and 50, while HPS2 pulmonary fibrosis is more prevalent in children and young adults." (PMID 39457053, 2024). "Lung fibrosis is the leading cause of death among adults with HPS-1 and HPS-4 genetic types, which are associated with defects in the biogenesis of lysosome-related organelles complex-3 (BLOC-3), a guanine exchange factor (GEF) for a small GTPase, Rab32." (PMID 35739508, 2022). "Pulmonary fibrosis has been found in three genetic variants of HPS, including HPS1, HPS2, and HPS4." (PMID 39457053, 2024). "HPS1 and HPS4 subjects are more prone to develop pulmonary fibrosis during middle age, while HPS2 pulmonary fibrosis is more prevalent in children and young adults." (PMID 40387003, 2025). "Pulmonary Fibrosis has been appreciated in HPS-1 and HPS-4 patients, whose genetic defects are in biogenesis of lysosome-related organelle complex 3 (BLOC-3), which includes HPS1 and HPS4 proteins, and, less commonly, HPS-2 patients." (PMID 35370755, 2022). "For instance, HPS‐3, HPS‐5, and HPS‐6 have milder symptoms with respect to other HPS subtypes; they do not develop the pulmonary fibrosis and granulomatous colitis that are seen in patients with defective BLOC‐3 (HPS1 and HPS4), or the neutropenia that is present in defective AP‐3 (HPS2 and HPS10)." (PMID 40387003, 2025).
melanoma (2 papers, 2017 to 2022). A malignant, usually aggressive tumor composed of atypical, neoplastic melanocytes. "Silencing of the BLOC-3 subunits Hps1 and Hps4 results in the mislocalization of Rab32 and Rab38 and a reduction in pigmentation in a melanoma cell line." (PMID 28438206, 2017). "In the present study, we focused on B16-F1 melanoma cells and established several KO cells for key factors in melanogenesis, i.e., Tyr, Hps4, Rab27A, and Rab32/38, to determine whether the mechanisms of melanogenesis in melanocytes are retained in B16-F1 cells." (PMID 36430618, 2022).
oculocutaneous albinism (2 papers, 2013 to 2023). Oculocutaneous albinism (OCA) describes a group of inherited disorders of melanin biosynthesis characterized by a generalized reduction in pigmentation of hair, skin and eyes and variable ocular findings including nystagmus, reduced visual acuity and photophobia. "The biallelic-affected individuals lack the normal HPS4 proteins, and their absenteeism results in the non-maturation of melanosomes (oculocutaneous albinism) and platelet-dense granules (bleeding diathesis) in family ALB-10." (PMID 36672886, 2023).
Anorexia (1 paper, 2017). Lack of desire to eat (loss of appetite). "All the PCV2/HPS4 coinfected piglets developed PMWS, characterized by dyspnea, anorexia, prostration and lose weight severely." (PMID 29157279, 2017).
co-infection (1 paper, 2017). "We firstly measured the clinical and peripheral blood changes of PCV2 and HPS4 co-infection, in order to analyze the synergistic influence on the virulence of PCV2 in piglets." (PMID 29157279, 2017). "Meanwhile, co-infection with PCV2 and HPS4 resulted in an increased amount of PCV2 genome loads in heart, liver, spleen, lung, kidney, lymph nodes, especially from the tonsil." (PMID 29157279, 2017). "This suggests that co-infection with PCV2 and HPS4 induce the exacerbation of system injuries and aggravates the secondary bacterial infection." (PMID 29157279, 2017). "Co-infection with PCV2 and HPS4 resulted in an increased amount of virus in serum and tissues, presented a slower generation and lower levels of antibodies against PCV2." (PMID 29157279, 2017). "Co-infection with PCV2 and HPS4 induce the exacerbation of system injuries and enhance the pathogenicity of PCV2 in piglets." (PMID 29157279, 2017).
cognitive deficits (1 paper, 2013). "Further analysis is required to reveal a putative role of HPS4 in the neurobiology related to the cognitive deficits in schizophrenia." (PMID 24168225, 2013).
hepatocellular carcinoma (1 paper, 2023). A malignant tumor that arises from hepatocytes. "Similarly, we found that HPS4 was also expressed in hepatocellular carcinoma cells including HEP3B217, HUH6, JHH6, JHH7, LI7, SNU423, and SNU449." (PMID 37781184, 2023).
liver cancer (1 paper, 2023). An epithelial or non-epithelial malignant neoplasm that arises from the liver. "Knockdown of HPS4 suppressed liver cancer cell proliferation and induced apoptosis." (PMID 37781184, 2023). "We found that HPS4 could reduce proliferation and apoptosis significantly in liver cancer cells; it may be a promising therapeutic target and biomarker for LIHC, and regulating its activity may be an effective treatment strategy." (PMID 37781184, 2023). "As HPS4 and a worse prognosis are strongly associated with LIHC, we further explored whether HPS4 contributes to liver cancer proliferation." (PMID 37781184, 2023). "HPS4, which could affect proliferation and apoptosis of liver cancer cells, may be a promising therapeutic target and biomarker for LIHC." (PMID 37781184, 2023). "Regulation of HPS4 may offer novel strategies for precision treatment in liver cancer patients." (PMID 37781184, 2023). "There is still a lack of understanding of how HPS4 impacts proliferation or apoptosis of liver cancer cells." (PMID 37781184, 2023).
pyrexia (1 paper, 2017). "Among the PCV2/HPS4 coinfected piglets by clinical observation, 5 piglets exhibited prostration, pyrexia, lymphadenectasis and bloody ocular secretions at 3 DPI, and 3 piglets showed severe cough, dyspnea, anorexia and diarrhea at 6 DPI." (PMID 29157279, 2017).
schizophrenia (1 paper, 2013). A major psychotic disorder characterized by abnormalities in the perception or expression of reality. "Our present study demonstrated that genetic variants in HPS4 were associated with executive function in patients with schizophrenia and with working memory in healthy controls." (PMID 24168225, 2013). "As discussed in our previous study, an argument for the involvement of variants of HPS4, particularly rs9608491, in the susceptibility to schizophrenia awaits further research." (PMID 24168225, 2013). "The purpose of the present study was to investigate whether HPS4 is associated with cognitive functions in patients with schizophrenia and healthy controls and with the clinical profiles of patients with schizophrenia." (PMID 24168225, 2013). "We initially tested the association of five tagging SNPs in HPS4 with the clinical profiles and cognitive domains as measured by BACS-J in Japanese patients with schizophrenia, and the association of HPS4 SNPs with cognitive domains was also tested in healthy controls." (PMID 24168225, 2013). "We investigated the association of variants of HPS4 with clinical symptoms and cognitive function in Japanese patients with schizophrenia (n = 240) and age-matched healthy control subjects (n = 240) with single nucleotide polymorphisms (SNP)- or haplotype-based linear regression." (PMID 24168225, 2013). "The aim of the present study was to investigate whether HPS4 is associated with cognitive functions in patients with schizophrenia and healthy controls and with the clinical profiles of patients with schizophrenia." (PMID 24168225, 2013). "In addition, we examined the association of HPS4 haplotypes and cognitive domains by using a sliding window approach in patients with schizophrenia and healthy controls." (PMID 24168225, 2013). "In the present study, which was based on our previous reports indicating an association of HPS4 with schizophrenia, we evaluated the associations of HPS4 with the clinical profiles of patients with schizophrenia and the cognitive functions of patients with schizophrenia and healthy controls." (PMID 24168225, 2013). "In addition, we have reported that two Japanese siblings who suffered from the comorbidity of major mental disorders, schizophrenia and major depression, and HPS harbored a nonsense mutation in HPS4." (PMID 24168225, 2013). "Our present results suggested that HPS4 may be involved in the executive function deficits of patients with schizophrenia." (PMID 24168225, 2013). "The Hermansky–Pudlak Syndrome Type 4 (HPS4) gene, which encodes a subunit protein of the biogenesis of lysosome-related organelles complex (BLOC)-3, which is involved in late endosomal trafficking, is associated with schizophrenia; however, its clinical relevance in schizophrenia remains unknown." (PMID 24168225, 2013).
infection (5 papers, 2014 to 2021). The state of being infected such as from the introduction of a foreign agent such as serum, vaccine, antigenic substance or organism. "Animal challenge experiments were performed to verify the disruption of TJ and the severe inflammatory response caused by HPS4-YC infection." (PMID 34674760, 2021). "Wild-type and HPS4-deficient mice were infected with Candida albicans, and the fungal burden in kidneys, the main organ affected by this pathogen, was evaluated 72 hours post-infection (p.i.)." (PMID 33523895, 2021). "HPS4-YC infection caused a severe inflammatory response in piglets." (PMID 34674760, 2021). "The total number of WBC, monocytes and lymphocytes in PCV2/HPS4 coinfected group was significantly decreased for about two weeks during the early stage of infection, which is consistent with the previous reports." (PMID 29157279, 2017). "The dramatic reduction of lymphocytes following infection reflected immunosuppression in the in PCV2/HPS4 coinfected piglets." (PMID 29157279, 2017). "Bacterial lipopolysaccharide (LPS) induced PCV2 replication in swine alveolar macrophages, hence, HPS4 may enhance the PCV2 replication at the site of infection, finally increases the amount of PCV2 viral loads in lymphoid tissue and immune organs significantly." (PMID 29157279, 2017). "In this study, Our data demonstrated that PCV2/HPS4 co-infected piglets had higher viral loads and a longer viremia duration in comparison with PCV2 single infection." (PMID 29157279, 2017). "At 2.5 h post infection, we were able to detect the BLOC-3 subunit HPS4 on 7%–8% of SCV." (PMID 33392103, 2020). "Here we report construction of a three-week-old naturally farrowed, colostrum-deprived (NFCD) piglet’s infection model and demonstrate that PCV2-infected piglets with the HPS4 coinfection increased the virulence of PCV2 and these pathogens interact acquired PMWS." (PMID 29157279, 2017). "Compared with the control group, HPS4-YC infection significantly decreased the TEER at 8, 12, 18 and 24 h after infection, and there was no significance at 4 h and 6 h post-infection of HPS4-YC, indicating that HPS4-YC infection gradually reduced the TEER value." (PMID 34674760, 2021).
HPS4 also shares sentences with these, for which no sentence is quoted: Hermansky-Pudlak syndrome (5 papers); albinism (3); bacterial infection (1); breast carcinoma (1); cancer (1); Chediak-Higashi syndrome (1); cholestasis (1); gastric cancer (1); Griscelli syndrome (1); infectious disease (1); lung carcinoma (1); Menkes syndrome (1); mental retardation (1); metabolic disorder (1); neurodegenerative disease (1); neurological disorders (1); Nystagmus (1); oculocutaneous albinism type 1 (1); pericardial effusion (1); respiratory failure (1); restrictive lung disease (1); tumor (1).